CALR (calreticulin)
Diseases named in the same sentence as CALR in open-access papers (continued):
Sharing a sentence is not in itself a finding about the gene and the disease.
cancer (418 papers, 1996 to 2026). A tumor composed of atypical neoplastic, often pleomorphic cells that invade other tissues. "Current research indicates that mutations in exon 9 of CALR are promising targets for cancer immunotherapy." (PMID 40568201, 2025). "During ICD, dying cancer cells release a series of damage-associated molecular patterns (DAMPs), such as calreticulin (CALR), high mobility group box 1 (HMGB1), and ATP." (PMID 41346575, 2025). "Therapeutic cancer vaccination with a peptide derived from CALR exon 9 mutations, or the mutant-CALR peptide vaccine combined with keyhole limpet hemocyanin and poly-ICLC, can induce strong cellular immune responses in patients with CALR-mutant MPN." (PMID 41268532, 2025). "The secondary objectives of our work are to analyze HLA-I and -II pathway genes in blood cells harboring CALR mutation, as downregulation of those pathways had been recognized as one of the main mechanisms for immune escape by cancer cells." (PMID 39351227, 2024). "ICD is associated with the release of various damage-associated molecular patterns (DAMPs) from dying cancer cells, including calreticulin, ATP, annexin A1, type 1 interferon, and high-mobility group box." (PMID 39726713, 2024). "An bioinformatics analysis of CALR data from public databases reveals that mutations of CALR were widely present in tumors, indicating a broad association with various cancers." (PMID 39479348, 2024). "Following selinexor incubation, we observed no significant change in the surface expression of ULBP-1, ULBP-2/5/6, MIC-A/B, CD54 (ICAM-1), B7-H6, or externalised calreticulin (ecto-reticulin), recently identified as the cancer associated ligand for NKp46." (PMID 37528310, 2023). "Calreticulin is another type of DAMPs that has been implicated in eliciting an anticancer effect by initiating a cancer cell death-associated immune response and promoting the increased production of DCs and phagocytotic tumor cells." (PMID 37325669, 2023). "JAK2 and CALR mutations generate cancer-specific neoantigens that are recognized by effector T cells." (PMID 35603202, 2022). "HN-PIT causes necrosis of cancer cells, which release damage-associated molecular patterns (DAMPs) such as ATP, calreticulin, and high mobility group box 1 (HMGB1)." (PMID 36139573, 2022). "Proteins associated with poor prognosis of cancer were significantly expressed in the diabetic group, except calreticulin and alpha-enolase." (PMID 35454982, 2022). "Aging neutrophils and surviving cancer cells are susceptible to be labeled by CALR which is secreted from macrophages, thus releasing the "eat me" signal." (PMID 34910788, 2021). "Therapeutic cancer vaccination against mutated CALR was suggested as a new treatment modality in CALR-mutated MPN." (PMID 34944059, 2021). "Increased expression of calreticulin on the cell surface sends an “eat me” signal to the cells of the immune system and is a causative agent of phagocytosis and destruction of the cancer cells." (PMID 33799560, 2021). "In CALR, cancer mutations alter the C-terminal domain-sized low complexity region, altering Ca2+ binding and protein localization." (PMID 33806614, 2021). "More importantly, to deeply understand the association between CALR and immune regulation, the potential relevances of CALR to multiple cancer immunoinhibitors were further analyzed across 30 cancer types." (PMID 32508042, 2020). "We demonstrate that in TTFields-treated cancer cells, damage-associated molecular patterns including high-mobility group B1 and adenosine triphosphate are released and calreticulin is exposed on the cell surface." (PMID 32144446, 2020). "While cholesterol biosynthesis is broadly increased across numerous cancers, including hematological cancers, CALR has also been directly linked to cholesterol biosynthesis." (PMID 33239297, 2020). "ER stress-mediated cell surface presentation of calreticulin (CRT) has emerged as a damage-associated molecular pattern (DAMP) of potential importance in cancer." (PMID 31133013, 2019).
cancer (continued). "Of note, calreticulin, a multifunctional chaperone protein, is linked to better prognosis of different types of cancers, indicative of its dual role in thermoresistance and ICD." (PMID 31814876, 2019). "These downstream genes that have an active contribution towards the malignant transformation of cancer cells are possibly the actual targets of calreticulin-associated pro-invasive effects and will need to be further evaluated in future studies." (PMID 27418879, 2016). "For example, anthracycline used in cancer chemotherapy induces calreticulin exposure in cancer cells within one hour, preceding the apoptosis-associated phosphatidylserine exposure." (PMID 25230046, 2014). "CALR defects, for instance, are associated with preneoplastic myeloproliferation in cancer." (PMID 40113210, 2025). "This helps the immune system destroy cancer cells and improve outcomes in CALR mutation+ MPNs." (PMID 41268532, 2025). "Clinically, this duality offers both a challenge and an opportunity: while surface-exposed CALR in cancer associates with favorable outcomes, high levels of soluble CALR may serve as a marker of therapeutic resistance." (PMID 40650935, 2025). "Oncolytic virus treatment has been reported to induce ICD in cancer cells because cancer cells infected with oncolytic virus release both pathogen-associated molecules and damage-associated molecules, such as ATP, calreticulin, and high mobility group box 1 (HMGB-1)." (PMID 38745748, 2024). "Additionally, CALR mutations increase protein secretion and bind to CALR receptors on antigen-presenting cells, limiting their ability to phagocytize cancer cells that express wild-type CALR and promoting immune evasion." (PMID 39519157, 2024). "Targeting STC-1 and its interaction with calreticulin may be an approach to enable patients to be susceptible to cancer immunotherapy." (PMID 36882399, 2023). "Another probable mechanism responsible for secondary malignancies development in MPNPh‐ includes immunosuppressive effects mediated by exon‐9‐mutated CALR released from the malignant cell, resulting in the inhibition of phagocytosis of dying cancer cells by dendritic cells." (PMID 36606310, 2023). "As reported, calreticulin plays important roles in shrimp antiviral immunity via MjsvCL (M. japonicus stomach virus–associated C-type lectin)–calreticulin pathway, as well as functions in cellular proliferation in cancer." (PMID 36761772, 2023). "CALR mutation was frequently detected in different cancer types." (PMID 35418980, 2022). "One of the main conclusions from this trial is that even though therapeutic cancer vaccination against an antigen derived from the CALR exon 9 mutations induces T-cell responses specific to the vaccination antigen, this does not translate into a molecular response." (PMID 33718228, 2021). "Additionally, CALR operates as a key damage-associated molecular pattern (DAMP) when it is translocated to the outer cell membrane of dying cancer cells." (PMID 33652860, 2021). "eIF2α phosphorylation is instrumental in the pre-apoptotic exposure of the endoplasmic reticulum chaperone calreticulin (CALR) on the cell surface, which stimulates the phagocytosis of portions of the dying cancer cell (with the tumor-associated antigen) by the dendritic cells (DCs)." (PMID 32455811, 2020). "In the future, CALR exon 9 mutations, as immunogenic neo-antigens, could be targets for cancer immune therapy." (PMID 31882869, 2019). "As such the CALR mutations generate an immunogenic antigen that could be used as target for cancer immune therapy." (PMID 30655510, 2019). "In addition, calreticulin has also been linked to malignant states, and as a major calcium homeostasis contributor, it plays a role in cancer invasion and metastasis." (PMID 27418879, 2016).
cancer (continued). "Elevated levels of HSP90 and CALR on the surface of neoplastic cells have been associated with clinical responses amongst 18 patients with relapsed indolent non-Hodgkin’s lymphoma treated with an autologous cancer cell-based vaccine." (PMID 26300886, 2015). "Moreover, calreticulin expression in carcinoma cells exposed to radiation was associated with the cell membrane (inset, black arrows)." (PMID 24480782, 2014). "Therefore, we performed an additional review of The Cancer Genome Atlas (TCGA) database, including datasets of >10,000 samples of 33 cancer types, searching for a possible co‐occurrence of the CALR driver mutations and mutations in the RAS family genes (HRAS, NRAS, and KRAS)." (PMID 36606310, 2023). "Once ICD was triggered by anti-cancer therapy, the release of many damage-associated molecular patterns (DAMPs), such as cell surface-exposed calreticulin (CALR), extracellular adenosine triphosphate (ATP), could drive the activation and maturation of innate and subsequent adaptive immune cells." (PMID 37036471, 2023). "Notably, the opposite situation existed in individual tumors, which may be caused by different mutation types and associated genes of CALR in different cancer types and needs further validation experimentally." (PMID 34910788, 2021). "Most APP genes were down-regulated in cancers, excluding the cochaperones calreticulin and calnexin, which participate in cancer pathology." (PMID 41477871, 2026). "Hydatid cyst wall antigens, hydatid cyst fluid and antigen B, EgKI- 1, T. cruzi epimastigote lysates, and recombinant T. cruzi calreticulin have exhibited similar promising anti-cancer effects, highlighting their potential as safe therapeutic agents." (PMID 40247360, 2025). "This protein duo is also involved in ICD, as BAX/BAK activation is essential for CALR exposure during cancer death by chemical and physical means." (PMID 41304887, 2025). "Mistletoe extracts trigger endoplasmic reticulum stress, leading to calreticulin exposure in 18–51% of cancer cells and a 7-fold increase in adenosine triphosphate (ATP) release." (PMID 40864825, 2025). "Biomarkers linked to DSS were found in eight cancer types, with CALR, FOXP3, and NT5E identified in at least three cancers." (PMID 41150760, 2025). "For PFS, biomarkers were detected in 10 cancer types, with CALR, CASP8, FOXP3, and LY96 consistently identified in at least three cancers." (PMID 41150760, 2025). "Calreticulin exposure on ER-stressed cancer cells is recognized by natural killer (NK) cells, stimulating NK-mediated cell lysis." (PMID 41225536, 2025). "The study also found that both nanoparticles can activate the immune system through photothermal therapy (PTT), which is expected to express surface CRT (Calreticulin) protein on dying cancer cells." (PMID 40922752, 2025). "This uncovers a dual role for CALR as immune activator or repressor, depending on its form and context, with distinct implications for cancer immunity." (PMID 40650935, 2025). "Recent research has further emphasized CALR’s role in activating dendritic cells and promoting cross-priming of cytotoxic T cells, particularly in the context of cancer immunotherapy." (PMID 40769969, 2025). "This was corrected through IHC testing, which confirmed the mesothelial cell lineage (calreticulin-positive, WT-1-positive, D2-40-positive) and excluded cancer markers (e.g., PAX-8-negative)." (PMID 41395612, 2025). "The externalization of calreticulin serves as a key “eat me” signal, actively promoting the recognition and engulfment of dying cancer cells by dendritic cells, which in turn drives their maturation." (PMID 40642535, 2025). "Specifically, TAP1, TAP2, TAPBP, PSMB8, and CALR were significantly upregulated in 17, 14, 13, 15, and 15 distinct cancer types, respectively." (PMID 38297270, 2024).
cancer (continued). "ATO inducing autophagy,apoptosis, iron death, and necrotic apoptosis pathways in cancer contributed to ATP release, HMGB1 version, CALR exposure of cancer cells, and IFNβ1 secretion of T cells." (PMID 39445013, 2024). "It has been revealed that cancer cells succumb to immunogenic cell death and then expose intracellular CALR to the surface of their cell membranes." (PMID 38245510, 2024). "Immunogenic death of cancer cells occurs with the release of risk associated molecular pattern (DAMP) molecules, including high mobility group box 1 (HMGB1), calreticulin (CRT), heat shock protein 70 (HSP70), and adenosine triphosphate (ATP)." (PMID 39231199, 2024). "Surprisingly, longitudinal FC analysis showed a decrease in CALR expression in TKIs-treated settings at later timepoints, which is likely due to cancer cell adaptation to chronic stressful stimuli." (PMID 39767726, 2024). "Very recently, it was reported that human and murine NK cells recognize externalized calreticulin in cancer cells under endoplasmic reticulum (ER) stress via NKp46, a major activating NK receptor, followed by the killing of cancer cells." (PMID 38474078, 2024). "For example, thapsigargin (Tha) and tunicamycin restore the immunogenicity of CDDP-induced cancer cell death through ER stress-induced CALR exposure." (PMID 39090653, 2024). "While CALR exposure on cancer cells positively correlates with overall and progression-free survival (PFS), elevated HMGB1 levels has been associated with poor outcomes in some trials." (PMID 39572927, 2024). "On the other hand, recent studies have unveiled the promising role of CALR as a protein in cancer treatment." (PMID 38245510, 2024). "According to in vivo and in vitro experiments, radioimmunotherapy based on R837/BMS@Au8 nanoparticles can increase calreticulin expression on of cancer cells, reactive oxygen species generation, and DNA breakage and decrease colony formation." (PMID 38183048, 2024). "Results showed that the release of adenosine triphosphate (ATP) and high-mobility group box 1 (HMGB1), and the expression level of extracellular calreticulin (CRT) in BLNs-treated cancer cells were significantly higher than those in the control." (PMID 38589867, 2024). "Blocking CD47 with anti-CD47 antibodies disrupts this inhibitory interaction, allowing the pro-phagocytic signal from CALR to dominate and facilitate the destruction of cancer cells." (PMID 39682299, 2024). "Regarding eat-me signals expressed by infected cancer cells, HSV-1 expressing GM-CSF infection induced calreticulin expression in different cancer cell lines." (PMID 39196415, 2024). "On one hand, BLNs up-regulate the expression of calreticulin, an “eat me” signal on the surface of cancer cells, thus promoting macrophage phagocytosis of cancer cells." (PMID 38589867, 2024). "CD47 blocks CALR-mediated phagocytosis and is upregulated when there are high levels of CALR expression on cancer cells." (PMID 38786045, 2024). "Although CALR can be induced on cancer cells, macrophages can also release CALR, which binds to cancer cells and triggers macrophage phagocytosis." (PMID 39767726, 2024). "In present study, we thus investigated the underrated role of CALR in NB by unprecedentedly uncovering CALR-mediated regulation of radioresistance and cancer stemness." (PMID 36644580, 2023). "Carboplatin, paclitaxel, and pemetrexed, which are used in CIT for NSCLC, promote antigen presentation to dendritic cells by translocating the endoplasmic reticulum-derived calreticulin to the cancer cell surface." (PMID 37894357, 2023). "ICD is indicated by a hallmark signature that involves induction of endoplasmic reticulum (ER) stress, followed by eIF2A phosphorylation-dependent exposure of normally ER resident proteins such as calreticulin on the plasma membrane of the dying cancer cells." (PMID 38069222, 2023).
cancer (continued). "We have demonstrated that the mutant C-terminus of mutant CALR is a cancer neo-antigen as the mutations are immunogenic, and both CD4+ and CD8+ T cells specific for peptides derived from the mutant CALR C-terminus recognize and kill autologous CALRmut cells." (PMID 37662956, 2023). "Collectively, our current study unraveled a new notion of utilizing CALR expression in malignant NB to diminish cancer stemness and mitigate radioresistance to achieve favorable therapeutic outcome for NB." (PMID 36644580, 2023). "In this study, we have assessed presentation of three hallmark factors for immunogenic cell death – namely release of HMGB1, secretion of ATP and surface-presentation of CALR – in human cancer cell lines after treatment with radiation and ATR inhibitors." (PMID 37346039, 2023). "Extracellular calreticulin has also been identified as pro‐phagocytic signal on the surface of several human cancers as well as vital for the immunogenic cell death of cancer cells." (PMID 37424156, 2023). "Both T. cruzi calreticulin and host extracellular calreticulin likely affect the immune response in cancer by similar mechanisms." (PMID 37424156, 2023). "We have shown that CALR interacts with CD47, an integrin-associated transmembrane protein, which stimulates the escape of cancer cells from immune surveillance." (PMID 36943734, 2023). "Our goal was to clarify if T cells specific to mutant CALR enrich in the bone marrow in patients after completion of therapeutic cancer vaccination against mutant CALR." (PMID 37662956, 2023). "Upon stimulation, cancer cells release calreticulin (CRT), ATP, heat shock proteins (HSP), and high mobility group box 1, which facilitate the uptake of tumor antigens by antigen-presenting cells." (PMID 37907972, 2023). "We observed high-calreticulin cancer stem cells in the border region, suggesting they can be phagocytosed by the surrounding myeloid cells." (PMID 36672243, 2023). "CALR is reported as a pro-phagocytic protein with CD47, a transmembrane integrin-associated protein as its ligand, which prevents cancer cell phagocytosis." (PMID 36943734, 2023). "Downregulating CD47 on cancer cells discloses calreticulin(CRT) to macrophages and recovers their phagocytic activity." (PMID 36632842, 2023). "In TCGA database, the overall survival of all cancer patients was favored with a high level of CALR and a low level of CD47." (PMID 36943734, 2023). "ER stress-mediated calreticulin (CRT) cell surface presentation has emerged as a damage-related molecular pattern (DAMP) of potential importance in cancer." (PMID 37858217, 2023). "One study has reported the increase of calreticulin exposure on the surface of ferroptotic cancer cells, which, combined with higher emissions of HMGB1 and ATP, induced the activation and maturation of BMDCs to exert an antitumor effect." (PMID 37325669, 2023). "The release of antigens can activate the T-cells that detect the dying cancer cells exhibiting calreticulin (CRT) and phosphatidylserine (PS) on their surface." (PMID 36831197, 2023). "Simultaneously, RRX-001 reduces CD47 protein levels, aiding in preventing immune escape by calreticulin-rich cancer cells." (PMID 37951973, 2023). "Through binding with membrane glycans, calreticulin is anchored to the cancer cell surface, and it interacts with the low-density lipoprotein receptor-related protein 1 (LRP1) receptor present on phagocytes." (PMID 36882399, 2023). "CALR genetic alterations have been observed in several cancer types and correlated to a worse outcome." (PMID 38035116, 2023). "The pool of calreticulin (ER versus extracellular and/or Ca2+ handling by calreticulin) responsible for the beneficial or detrimental role in cancer remains to be determined." (PMID 37424156, 2023). "IL8, for example, increases the immunogenicity of dying cancer cells by translocating calreticulin to the cell surface." (PMID 37078828, 2023).